SIAH1 (siah E3 ubiquitin protein ligase 1)
Diseases named in the same sentence as SIAH1 in open-access papers (continued):
Sharing a sentence is not in itself a finding about the gene and the disease.
lung cancer (8 papers, 2017 to 2025). A malignant neoplasm involving the lung. "Exosomal LINC00963 of lung cancer cells enhances the metastatic potential of lung cancer cells by decreasing the expression of seven in absentia homolog 1 (SIAH1) while increasing the zinc finger E-box-binding homeobox 1 (ZEB1) expression level." (PMID 37242707, 2023). "Our findings suggested an essential role for the SIAH1/HMGCR axis in lung cancer chemoresistance." (PMID 37062828, 2023). "Our data indicated that SIAH1 / HMGCR is a potential key driver of chemoresistance in lung cancer." (PMID 37062828, 2023). "SIAH1, an E3 ubiquitin ligase, ubiquitinates HMGCR and regulates cholesterol synthesis, thereby inhibiting lung cancer progression and enhancing drug sensitivity through cholesterol synthesis." (PMID 39944823, 2025). "This study indicates that lung cancer patients with lower HMGCR levels may lead to a better prognosis and provide a potential treatment by SIAH1 overexpression for lung cancer patients with cisplatin resistance." (PMID 37062828, 2023).
glioblastoma (7 papers, 2018 to 2024). The most malignant astrocytic tumor (WHO grade IV). "Downregulation of the HIPK2 inactivator SIAH1 significantly ameliorates temozolomide‐induced glioblastoma cell apoptosis." (PMID 38186203, 2024). "It is interesting that the inhibitors of HIPK2 and SIAH1 are often overexpressed in glioblastoma, which would impede activation of HIPK2 after DNA damage." (PMID 38068493, 2023). "Significantly elevated in the advanced stages of Glioblastoma (GBM), PHF19 was reported to block the degradation of β-catenin via transcriptional repression of SIAH1 and promote the progression of GBM." (PMID 35069553, 2021).
colon cancer (4 papers, 2013 to 2020). "We reported previously that hexachlorophene accelerated β-catenin decomposition by activating the expression of Siah-1 in HCT116 and LS174T colon cancer cells." (PMID 32294900, 2020). "When Zeb1 expression was normalized to that of Fbxo45, but not Siah1, the DFS of colon cancer patients with higher Zeb1/Siah1 levels was statistically significantly reduced compared to patients with lower values." (PMID 30979372, 2019). "Normalization to Fbxo45, but not Siah1, further significantly reduced the OS of colon cancer patients." (PMID 30979372, 2019).
diabetes (4 papers, 2014 to 2023). "Intriguingly, it has been shown that the high protein levels of HIPK2 in a mouse model of diabetes depend on the downregulation of E3 ubiquitin ligase Siah-1 (seven in absentia homolog-1), which is known to induce HIPK2 protein degradation." (PMID 37345014, 2023). "We found that mRNA levels of Nox4 were significantly increased in the glomeruli of the diabetic mice compared to control, but Seven in Absentia Homolog 1 (Siah1) mRNA expression was significantly decreased in diabetes compared to control." (PMID 27941951, 2016). "As shown in the general heat map, major clusters identified to be Siah1/2-dependent included diabetes and metabolism, in addition to hypoxia signaling." (PMID 24809345, 2014).
epithelial ovarian cancer (4 papers, 2020 to 2024). "Consistently, SIAH1 is reported to be significantly downregulated in various cancer types, including drug-resistant ovarian cancer." (PMID 35273154, 2022). "The colocalization of cytoplasmic SIAH1 and YBX-1 in ovarian cancer cells was detected by confocal microscopy, supporting the direct interaction between SIAH1 and YBX-1 proteins." (PMID 35273154, 2022). "In addition, in epithelial ovarian cancer (EOC), SIAH1 (seven in absentia homolog 1), a ubiquitinating ligase, ubiquitinates YBX1 at K304 via the RING domain, making EOC sensitive to cDDP and inhibiting cancer cell proliferation, invasion, and migration." (PMID 38343637, 2024). "The E3 ligase SIAH1 is deregulated in human cancers and correlated with poor prognosis, but its contributions to chemoresistance in epithelial ovarian cancer (EOC) are not evident." (PMID 35951361, 2022).
glioma (4 papers, 2018 to 2025). A benign or malignant brain and spinal cord tumor that arises from glial cells (astrocytes, oligodendrocytes, ependymal cells). "Nevertheless, it may also suppress glioma cell migration and invasion through Siah1-mediated cytoplasmic downregulation of p27ˆKip1." (PMID 40167359, 2025).
Parkinson disease (4 papers, 2020 to 2025). A progressive degenerative disorder of the central nervous system characterized by loss of dopamine producing neurons in the substantia nigra and the presence of Lewy bodies in the substantia nigra and locus coeruleus. "SIAH1, a member of the same family as SIAH2, has been reported to promote mitophagy through the PINK1-synphilin-1-SIAH1 signaling axis, contributing to the progression of Parkinson’s disease." (PMID 40004017, 2025). "Intriguingly, mammalian SIAH1, an E3 ligase implicated in Parkinson’s disease (PD) and enriched in Lewy bodies, has not been studied in the context of UPRmt regulation or Aβ proteotoxicity." (PMID 40349774, 2025). "Among them, it has been proposed that the E3-ligase Siah1/2 (seven in absentia homolog-1/2), recruited on mitochondria after depolarization and able to ubiquitinate mitochondrial proteins, activates mitophagy in different pathological conditions like Parkinson’s Disease and cerebral ischemia." (PMID 39875361, 2025).
gastric cancer (3 papers, 2010 to 2020). A primary or metastatic malignant neoplasm involving the stomach. "Since this work uncovers a new mechanism of H. pylori-induced degradation of cell membrane-associated β-catenin, we believe that Siah1 is a crucial factor regulating gastric cancer progression and metastasis." (PMID 28481365, 2017). "In this study, we identified that the carcinogenic bacterium H. pylori increased ETS2 transcription factor-mediated Siah1 protein expression in gastric cancer cells (GCCs) MKN45, AGS and Kato III." (PMID 28481365, 2017). "We sought to investigate the effect of H. pylori infection on the expression and activity of Siah1 protein in the infected gastric cancer cells (GCCs)." (PMID 28481365, 2017). "As Siah1 lacks Twist1-binding site, we speculate that these isotypes can still be differentially regulated since ETS2 and Twist1 expression might vary depending on the staging of gastric cancer." (PMID 28481365, 2017).
viral infection (3 papers, 2018 to 2026). "To analyze the relevance of the ICP0:SIAH-1 interaction in the context of viral infection we introduced the VxP1 and/or VxP2 mutations into both ICP0 coding regions of a full-length HSV-2 genome." (PMID 30080903, 2018).
brain ischemia (2 papers, 2014 to 2025). Diminished or absent blood supply to the brain caused by obstruction (thrombosis or embolism) of an artery resulting in neurologic damage. "In agreement, the increased expression of Siah1 coincided with decreased PHD3 expression following cerebral ischemia." (PMID 24809345, 2014). "To further determine the role of Siah1/2 in cell death induced by severe ER stress such as ischemia, we used the middle cerebral artery occlusion model (MCAO), a surgical model of cerebral ischemia known to induce severe ER stress and cell death." (PMID 24809345, 2014).
breast tumor (2 papers, 2010 to 2016). "Congruently, the expression of SIAH1 was significantly increased in 53 % of miR-944 deficient breast tumors in comparison with normal adjacent tissues." (PMID 27377268, 2016). "Moreover, SIAH1 was upregulated in 75 % of miR-944-deficient breast tumors." (PMID 27377268, 2016). "In our study, we observed that SIAH1 expression was decreased in almost half of breast tumors analyzed, which agreed with previous studies." (PMID 27377268, 2016). "In breast tumor tissues SIAH-1 expression was less intense and more heterogeneous showing a more diffuse pattern, and nuclei were also frequently stained." (PMID 20144232, 2010). "Moreover, miR-944 and SIAH1 expression showed an inverse correlation in breast tumors." (PMID 27377268, 2016). "Interestingly, in all breast tumor tissues analyzed, variations in the Kid/KIF22 mRNA levels mirrored those seen with SIAH-1 mRNAs." (PMID 20144232, 2010).
Buratti-Harel syndrome (2 papers, 2025). "Buratti-Harel syndrome (BURHAS) is a rare autosomal dominant neurodevelopmental disorder caused by SIAH1 (Siah1 E3 ubiquitin ligase) variants, characterized by infantile hypotonia, global developmental delay, and variable multisystem involvement." (PMID 41574050, 2025). "Pathogenic monoallelic variants in SIAH1 underlie Buratti-Harel syndrome (BURHAS; MIM #619314), a neurodevelopmental disorder that remains rarely documented." (PMID 41574050, 2025). "Buratti–Harel syndrome (BURHAS) is a rare genetic condition caused by heterozygous pathogenic variants of the SIAH1 gene, with only five unrelated cases included in a single report in 2019." (PMID 41189745, 2025).
developmental delay (2 papers, 2025). "This is the first complete description of a phenotype and genotype of a patient with a novel heterozygous frameshift variant in SIAH1, and a first report of a Chilean individual with developmental delay, infantile hypotonia, and facial dysmorphism." (PMID 41189745, 2025). "Our findings advocate for SIAH1 inclusion in diagnostic gene panels for patients presenting with developmental delay, dysmorphic features, and multisystem anomalies." (PMID 41574050, 2025). "Herein, we describe a sporadic case of BURHAS presenting with developmental delay, dysmorphic features, limb muscle weakness, and distinctive neuroimaging abnormalities, associated with a novel de novo SIAH1 variant." (PMID 41574050, 2025). "This study expands the phenotypic and mutational spectrum of SIAH1-associated neurodevelopmental disorders (NDDs) by reporting a novel de novo missense variant (c.288C > G, p.Phe96Leu) in a pediatric patient presenting with developmental delay, dysmorphic features, and brain imaging abnormalities." (PMID 41574050, 2025).
osteosarcoma (2 papers, 2015 to 2024). A usually aggressive malignant bone-forming mesenchymal neoplasm, predominantly affecting adolescents and young adults. "Siah1 has been found to be upregulated in osteosarcoma, where it increases resistance to doxorubicin treatment; hence, a therapy targeting the HIF transcription factor in osteosarcoma should consider the inhibition of Siah1, to prevent its accumulation." (PMID 38534381, 2024).
cervical cancer (1 paper, 2019). A primary or metastatic malignant neoplasm involving the cervix. "Conversely, miR-135a was found to target SIAH1 to promote cell transformation in cervical cancer via the β-catenin pathway." (PMID 32010197, 2019).
colorectal tumor (1 paper, 2024). "In the mouse xenografts model, treatment with CK1δ/ε inhibitor SR3029 and knockdown of SIAH1 resulted in attenuated colorectal tumor growth via stabilizing AXIN1." (PMID 38419282, 2024).
cone-rod dystrophy (1 paper, 2020). Inherited retinal dystrophies that belong to the group of pigmentary retinopathies. "Our work outlines the first observation of a functional role for Siah1 and Cdhr1a during photoreceptor development, which may in future studies be utilized to examine the mechanism of cone-rod dystrophy pathogenesis." (PMID 33330480, 2020).
diffuse large B-cell lymphoma (1 paper, 2012). "SIAH1 (seven in absentia homolog 1) is known to be down-regulated in diffuse large B-cell lymphoma as the result of Epstein-Barr virus infection." (PMID 22429919, 2012).
Epstein-Barr virus infection (1 paper, 2012). An infection that is caused by Epstein-Barr virus. "A link between SIAH1 and NHLs was also found in the literature, when Epstein-Barr virus infection had been detected in the tumor." (PMID 22429919, 2012).
Flavivirus Infections (1 paper, 2020). Infections with viruses of the genus FLAVIVIRUS, family FLAVIVIRIDAE. "Flavivirus infection has been shown to activate several arms of the UPR, suggesting that SIAH1 expression may be induced in cells infected with DENV2." (PMID 32117091, 2020).
gastric adenocarcinoma (1 paper, 2017). "ETS2 and Siah1 were assessed in gastric adenocarcinoma, antral biopsy samples (stage III, rapid urease test-positive) collected from consenting patients." (PMID 28481365, 2017). "Siah1 protein level was also noticeably higher in gastric adenocarcinoma biopsy samples as compared to non-cancerous gastric epithelia." (PMID 28481365, 2017).
gastroesophageal reflux (1 paper, 2025). "We report the case of a Chilean 9-year-old girl presenting with congruent phenotypic characteristics: mild neurodevelopmental delay, dysmorphic features, infantile hypotonia, and gastroesophageal reflux with a novel heterozygous, de novo variant in the seven in absentia homolog 1 (SIAH1) gene." (PMID 41189745, 2025).
Infertility (1 paper, 2022). "This search revealed that in the case of NANOS1 overexpression, three infertility related genes (CREBBP, CCNB1, and NPAS2) and five cancer-germ cell genes (CENPL, ERCC6L, KIF18A, SIAH1, and TRIM71) were present in three clusters." (PMID 35743036, 2022).
liver cancer (1 paper, 2024). An epithelial or non-epithelial malignant neoplasm that arises from the liver. "We have revealed the molecular mechanism by which loss of SIAH1 in liver cancer regulates the protein stability of FASN through two pathways: promoting deubiquitination and reducing ubiquitination." (PMID 39075049, 2024). "Collectively, these results revealed that SIAH1 acts as a tumor suppressor in mice, and loss of SIAH1 may be an important event during the development and progression of liver cancer in mice." (PMID 39075049, 2024). "Oncologically, studies showed that SIAH1 was associated with the involvement of liver cancer." (PMID 39075049, 2024). "Studies have shown that SIAH1 plays an important role in the occurrence and development of liver cancer." (PMID 39075049, 2024). "To confirm this concept, we examined the regulation of FASN–FSCN1 pathway and filopodia formation in liver cancer cells by manipulating SIAH1." (PMID 39075049, 2024). "In this study, we found SIAH1 is lower expressed in liver cancer." (PMID 39075049, 2024). "To confirm whether SIAH1 affects filopodia formation in liver cancer cells by regulating FASN, we detected the regulation of FSCN1 by SIAH1." (PMID 39075049, 2024). "Furthermore, an orthotopic model of liver cancer was established using Hep1-6 overexpressed SIAH1." (PMID 39075049, 2024). "To explore the mechanism by which SIAH1 degrades ADRM1, we first determined the interaction between them in liver cancer cells." (PMID 39075049, 2024). "Our results reveal a novel mechanism for FASN accumulation due to the low expression of SIAH1 in human liver cancer and suggest an important role of FASN in filopodia formation in liver cancer cells." (PMID 39075049, 2024). "Collectively, our findings suggest that the SIAH1-FASN–FSCN1 axis is crucial for filopodia formation in liver cancer cells, and this discovery provides a promising strategy for the treatment of liver cancer." (PMID 39075049, 2024). "To address this question, we analyzed the protein level of FASN in liver cancer cells when SIAH1 was overexpressed or silenced and found that overexpression of SIAH1 decreased the expression of FASN, while knockdown of SIAH1 increased it." (PMID 39075049, 2024). "It is speculated that SIAH1 may also be involved in the regulation of the FASN–FSCN1 pathway and filopodia formation in human liver cancer cells." (PMID 39075049, 2024). "The results showed that SIAH1 could decrease the expression of FSCN1 by directly ubiquitinating FASN, thereby inhibiting filopodia formation in human liver cancer cells, as well as cell invasion and migration." (PMID 39075049, 2024). "Clinically, SIAH1 was found to be downregulated in liver cancer samples, and there was a directly negative correlation between SIAH1 and ADRM1 protein levels in normal and liver cancer specimens." (PMID 39075049, 2024). "In terms of clinical protein expression correlation, the protein levels of SIAH1 and FASN exhibited a directly negative correlation in normal and liver cancer specimens." (PMID 39075049, 2024).
memory impairment (1 paper, 2021). "Accordingly, a previous conducted a study on H2 showed amelioration of TMT-induced spatial learning and memory impairment in mice by regulation of Siah-1." (PMID 34948107, 2021).
mesothelioma (1 paper, 2018). A usually malignant and aggressive neoplasm of the mesothelium which is often associated with exposure to asbestos.
nasopharyngeal carcinoma (1 paper, 2018). A carcinoma arising from the nasopharyngeal epithelium. "Specifically, LMP1 was shown to enhance the synthesis of HIF-1α and the expression of HIF-1α-responsive genes in a nasopharyngeal carcinoma (NPC)-derived cell line, which could be attributed to enhanced degradation of prolylhydroxylases (PHD) 1 and 3 mediated by SIAH1." (PMID 30395643, 2018).
nephropathies (1 paper, 2017). "Siah1 degrades homeo-domain interacting protein kinase 2 (HIPK2), a key molecule in the induction of kidney fibrosis and the epithelial-to-mesenchymal transition in various nephropathies such as human immunodeficiency virus (HIV)-associated kidney disease." (PMID 28859164, 2017).
preeclampsia (1 paper, 2010). Preeclampsia is a hypertensive disorder of pregnancy that is characterized by new-onset hypertension with proteinuria presenting after 20 weeks of gestation, and depending on mild or severe forms may initially present with severe headache, visual disturbances, and hyperreflexia. "In particular, we found decreased SIAH-1 and SIAH-2 mRNA levels in early-onset, but not late-onset, preeclamptic placentae, further emphasising the lack of placental oxygen sensing in the most severe form of preeclampsia." (PMID 20967267, 2010).
proteopathies (1 paper, 2025). "Collectively, these findings establish the SIAH-1/DVE-1 axis as a conserved proteostasis regulator and highlight ubiquitin-dependent mitochondrial quality control as a potential therapeutic target for AD and related proteopathies." (PMID 40349774, 2025).
pulmonary fibrosis (1 paper, 2020). Chronic progressive interstitial lung disorder characterized by the replacement of the lung tissue by connective tissue, leading to progressive dyspnea, respiratory failure, or right heart failure. "We initially examined repression of the E3 ubiquitin ligases SIAH1, SMURF1, and SMURF2, which have been identified as targets of miR-424 in several cancers as well as pulmonary fibrosis." (PMID 32117091, 2020).